RDX (radixin)
Diseases named in the same sentence as RDX in open-access papers (continued):
Sharing a sentence is not in itself a finding about the gene and the disease.
osteoporosis (1 paper, 2019). A condition of reduced bone mass, with decreased cortical thickness and a decrease in the number and size of the trabeculae of cancellous bone (but normal chemical composition), resulting in increased fracture incidence. "Based on previous studies, ATF2, FBXW7, and RDX were osteoporosis-related DEGs." (PMID 30809532, 2019).
osteosarcoma (1 paper, 2016). A usually aggressive malignant bone-forming mesenchymal neoplasm, predominantly affecting adolescents and young adults. "Phosphatydil inositol bisphosphate (PIP2), belonging to the Phosphoinositide (PI) signal transduction pathway, was related to the regulation of ezrin, an ezrin–radixin–moesin protein involved in metastatic osteosarcoma spread." (PMID 27026853, 2016).
Parkinsonism (1 paper, 2025). Characteristic neurologic anomaly resulting from degeneration of dopamine-generating cells in the substantia nigra, a region of the midbrain, characterized clinically by shaking, rigidity, slowness of movement and difficulty with walking and gait. "Here, we found that the most common Parkinsonism gene mutation, LRRK2 G2019S, enhances the phosphorylation of the ERM proteins (Ezrin, Radixin, and Moesin), components of the perisynaptic astrocyte processes in a subset of cortical astrocytes." (PMID 39253496, 2025).
renal carcinoma (1 paper, 2012). A carcinoma arising from the epithelium of the renal parenchyma or the renal pelvis. "An increase of CD44 protein was observed in Caki-1 renal cancer cells following hypoxia, which was attributed to the Rho kinase-mediated activation of ERM (Ezrin, Radixin, Moesin) proteins during hypoxia, since ERM proteins are associated with the cytoplasmic domain of CD44." (PMID 22937154, 2012).
schwannoma (1 paper, 2025). A benign, usually encapsulated slow growing tumor composed of Schwann cells. "It is now unanimously accepted in the literature that the origin of schwannomas is associated with a mutation in a cytoskeletal protein called Merlin, Neurofibromin 2, or schwannomin, which belongs to the ERM (Ezrin–Radixin–Moesin) protein family and is regulated by the tumor suppressor gene NF2." (PMID 40722574, 2025).
thymoma (1 paper, 2008). A neoplasm arising from the epithelial cells of the thymus. "The ezrin, radixin and moesin proteins, involved in intracellular anchoring of cell membrane proteins to the cytoskeleton, were detected by both the MG-thymoma MS samples and the exon arrays." (PMID 18545673, 2008). "MG-thymoma radixin median exonic change increased but ezrin and moesin decreased, reflecting specific regulation for each member of this protein family." (PMID 18545673, 2008).
cancer (42 papers, 2009 to 2026). A tumor composed of atypical neoplastic, often pleomorphic cells that invade other tissues. "The pathogenic function of radixin has been found in central nervous system diseases, peripheral nerve injury, and cancers." (PMID 39457653, 2024). "The regulation of integrin-associated protein CD47 by radixin has been linked to poor prognosis of cancers." (PMID 39457653, 2024). "The potential of radixin as a therapeutic target in neurodegenerative diseases and cancer was also discussed." (PMID 39457653, 2024). "Ezrin, a member of the ezrin–radixin–moesin protein family, is strongly expressed in many types of cancers." (PMID 36156321, 2023). "PROM1 is an important surface marker of normal and cancer stem cells and has several binding partners, such as Actin, Radixin, PI3K, and HDAC623,34–36." (PMID 36038590, 2022). "The cytoplasmic C-terminal domain of PROM1 binds to PI3K and radixin, maintaining cancer stem cell properties and regulating glucagon-induced PKA activity, respectively." (PMID 36266314, 2022). "ERM proteins (Ezrin, Radixin, Moesin) are known to provide a physical connection between actin cytoskeleton and plasma membrane, thereby participating in cell migration and cancer metastasis." (PMID 36175399, 2022). "Within these genes, AKAP9, CENPE, PRKCI, RDX, RECQL, and USO1 have also been reported to be associated with cancer progression." (PMID 31426369, 2019). "Interaction of CD44 with growth factor receptors stimulates the proliferation and invasion of cancer cells; however, its interaction with ezrin/radixin/moesin proteins activates the tumor suppressor, merlin, to inhibit cancer growth." (PMID 26572077, 2015). "An increase in miR-409-3p reduced the migration and invasion of cancer cells in vitro, most likely via the pro-metastatic gene radixin (RDX) and the PHF10 gene." (PMID 23478435, 2013). "The NEP N-terminus also affects tumor formation by competing with the hyaluronan receptor CD44 for Ezrin/Radixin/Moesin (ERM) binding thereby reducing the invasive capacity of cancer cells." (PMID 20957047, 2010). "For example, we found a cancer-related D695Y mutation in the tumour suppressor Breast cancer type 1 susceptibility protein (BRCA1) that creates novel binding sites for the Yx[FILV]-binding FERM domains of Moesin (MSN) and Radixin (RDX)." (PMID 39009827, 2024). "The results implicate that targeting radixin and ezrin may facilitate finding novel treatments for colorectal and other types of cancers." (PMID 39457653, 2024). "The 4.1 proteins family is characterized by FERM (Four-point-one, Ezrin, Radixin, Moesin) domains, many of which have related functions in influencing the biologic characteristics of tumor cells, as reported mainly with regard to cancer progression." (PMID 27487132, 2016). "Clinical studies have observed the expression pattern of radixin in different cancers." (PMID 25136657, 2014). "In addition to the possibility that RDX-induced miRNAs are involved in carcinogenesis, we found that several potential miRNA-targeted genes are involved in cancer development." (PMID 19270793, 2009). "Understanding the mechanisms by which radixin mediates the cell signaling pathways for its biological activities may hold a great opportunity to find therapeutic strategies for diseases in the nervous system, cancers, and other diseases." (PMID 39457653, 2024). "Thus, PD-L1 expression modulation in the plasma membrane of cancer cells by therapeutic agents targeting ezrin and/or radixin may represent a novel treatment strategy to boost the efficacy of PD-1/PD-L1 blockade therapies in CRC." (PMID 34577564, 2021). "Proteins of the ezrin, radixin, and moesin (ERM) family are key regulators of cell morphogenesis and essential determinants of cancer cell metastasis." (PMID 41844278, 2026).
cancer (continued). "Overexpression of CD44 has been observed in many types of cancer, and the interaction between CD44 and ezrin, radixin, and moesin links the actin cytoskeleton to the plasma membrane and the extracellular matrix." (PMID 32679746, 2020). "It is well known that ERM complex (Ezrin, Radixin and Moesin) are cytoskeletal molecules connected to CD44 C-terminal domain and are believed to be closely related to cancer malignancy." (PMID 33292278, 2020). "Different important target genes have been validated in different cancers, such as the transcriptional regulator PHF10, the pro-metastatic gene radixin, the pro-angiogenic gene angiogenin (ANG), the oncoprotein GAB1 and the pro-metastatic gene c-Met." (PMID 27057640, 2016). "Here, we have studied the intracellular dynamics of PTPD1, a FERM (four-point-one, ezrin, radixin, moesin) domain-containing PTP that is over expressed in cancer cells and potentiates EGFR signalling." (PMID 25062045, 2014). "Here, the authors suggest that the variations in malignant phenotypes between LGR5-positive cancer stem cells and LGR5-negative cells could be due to their distinct mechanical phenotypes observed in vitro, determined by the membrane to cortex attachment proteins Ezrin/Radixin/Moesin." (PMID 38637494, 2024).
tumor (41 papers, 2009 to 2025). "The implantation of radixin-deficient cells in mice also reduced the density of microvessels and inhibited tumor growth." (PMID 39457653, 2024). "Ezrin and Radixin were detected in murine brain tissue and HepG2 cells, underlining the tumor-associated Ezrin expression." (PMID 37928027, 2023). "The FERM domain, a member of the ezrin, radixin, and moesin family, is particularly noteworthy for its ligand-binding capabilities and potential to inhibit tumor growth." (PMID 39976799, 2025). "It was found that RDX—a cytoskeletal linker protein reported to promote tumor pathogenesis—was the only protein in the intersection." (PMID 37759298, 2023). "Like Ezrin and Moesin, Radixin is overexpressed in many tumor tissues and can modulate the viral infection process for several viruses by regulating stable microtubule function." (PMID 37371090, 2023). "In xenograft tumor models, Overexpression of RDX in MGC803 cells erased ICAM2-induced growth rate and tumor weight differences." (PMID 37759298, 2023). "By interacting with ezrin/radixin/moesin, S100P can promote trans-endothelial migration of tumor cells, thereby favoring metastasis." (PMID 37627239, 2023). "Previous studies showed that RDX was overexpressed and promoted tumor malignancy in several types of solid tumors." (PMID 37759298, 2023). "The knockdown of Radixin by shRNA in glioblastoma U251 cells was found to significantly inhibit tumor growth and upregulate thrombospondin-1 (TSP-1) and E-cadherin while downregulating MMP9." (PMID 37371090, 2023). "ICAM-3 is an adhesion molecule that can interact with LFA-1 extracellularly or ezrin/radixin/moesin intracellularly, contributing to tumor metastasis." (PMID 36059515, 2022). "Podoplanin has been reported to enhance tumour invasion by enhancing cell motility through interaction with actin in the cytoskeleton via proteins such as ezrin, radixin, and moesin." (PMID 31452946, 2019). "Moesin is a member of the ERM (ezrin, radixin and moesin) proteins that participate in cell migration and tumor invasion through transductional signals sent to actin filaments by glycoproteins, such as podoplanin." (PMID 29310601, 2018). "As a member of the ezrin-radixin-moesin (ERM) family, radixin is overexpressed in many tumor tissues." (PMID 25136657, 2014). "Exposure to RDX also induced aberrant expressions of other onco-miRNAs and tumor-suppressing miRNAs, such as let-7, miR-10b, miR-15, miR-16, miR-26 and miR-181, which regulated tumor pathogenesis or genes related to the cell cycle (e.g., TNKS)." (PMID 21592377, 2011). "Abnormal expression of RDX contributes to the development of several diseases and it may also promote tumor occurrence and progression by modulating the signaling pathways relevant to tumorigenesis." (PMID 37759298, 2023). "miRNAs may directly and/or indirectly (through regulating other genes) affect the action of RDX on tumor pathogenesis and neurotoxicity." (PMID 19270793, 2009). "Radixin is considered the dominant form of ERM protein in primary human hepatocytes, while ezrin was mainly found in immortal human tumor cell lines." (PMID 40723305, 2025). "It plays a pivotal role in tumor suppression by inhibiting invasion and migration via targeting the RDX gene (Radixin)." (PMID 37371047, 2023). "In summary, this study demonstrates the tumor-suppressive role of ICAM2 and its correlation with RDX in GC." (PMID 37759298, 2023). "The identified potential tumor suppressor genes included DAG1, SLC39A8, TMEM173/STING1, RDX, TJP1, CTNNB1, and SMC3." (PMID 36499305, 2022). "Previous experimental studies suggested the role of miR-let-7b in suppressing tumors, which works by inhibiting tumor proliferation, invasion, and adhesion via interacting with various genes named HMGA2, RDX, DIAPH2, Ras c-myc, and PKA133." (PMID 35831411, 2022). "Despite the considerable research undertaken on ezrin and moesin, the precise role of RDX in tumor development has not been revealed." (PMID 37759298, 2023).
tumor (continued). "As a tumor suppressor or tumor promoter, miR-let-7b has been found to halt cell proliferation, adhesion, and invasion by targeting Protein Code Gene (PKA1), Diaphanous Related Formin 2 (DIAPH2), Radixin (RDX), RAS, MYC, and High Mobility Group A2 (HMGA2) genes and their respective proteins." (PMID 34122072, 2021). "To date, the literature supports the tumor suppressor functions of DAG1, SLC39A8, TMEM173/STING1, TJP1, CTNNB1, and SMC3, but not RDX." (PMID 36499305, 2022). "Another importance is that gene silencing of ezrin, but not of radixin and moesin significantly decreased the cell surface expression of P-gp without affecting the levels of the ABCB1 mRNA in LS180 cells cultured at the acidic pH condition which mimics the actual tumor microenvironment." (PMID 33974673, 2021).
infection (6 papers, 2016 to 2022). The state of being infected such as from the introduction of a foreign agent such as serum, vaccine, antigenic substance or organism. "After infection, we detected EV markers such as Ezrin, Radixin and Moesin (ERMs), and other EV markers like Milk Fat Globule-EGF Factor 8 (MFG-E8, Lactadherin), but no contamination from other membrane compartments like the endoplasmic reticulum (CALNEXIN)." (PMID 36131943, 2022). "Taken together, the down regulation of Ezrin, Radixin and Moesin with ∆potABCD suggest a novel mechanism by which pneumococci can escape host innate immunity and spread infection in the lung by regulating the expression of ERM complex." (PMID 27247105, 2016). "EZR, MSN, and RDX mRNA levels were studied after 12, 24, and 48 h of infection." (PMID 36358519, 2022). "E-30 infection leads to a down-regulation of proteins such as RADIXIN, PFDN6, DYNLB1, and BRK1." (PMID 33321840, 2020). "At the cellular level, proteins like ICAM-1, TLR2 or Ezrin/Radixin were only up-regulated in CACs treated with the serum of asymptomatic patients at the highest peak of infection (PCR + /IgG −), but not with the serum of PCR −/IgG + individuals." (PMID 35397534, 2022).
neurological disorders (1 paper, 2014). "Since that miRNAs are highly conserved between humans and rats, this study should improve our understanding of the molecular mechanisms of RDX induced neurological disorders and diseases." (PMID 25559034, 2014). "Our results indicate that RDX could induce neurological diseases and neurotoxicity through regulating these miRNAs." (PMID 25559034, 2014).
RDX also shares sentences with these, for which no sentence is quoted: Hearing impairment (2 papers); adenocarcinoma (1); benign prostatic hyperplasia (1); central nervous system diseases (1); chordoma (1); colorectal cancer (1); congenital stationary night blindness (1); Ductal Carcinoma In Situ (1); dyschezia (1); fibrosarcoma (1); follicular thyroid carcinoma (1); head and neck squamous cell carcinoma (1); insulinoma (1); Jaundice (1); liver fibrosis (1); lymph node metastasis (1); metastatic prostate carcinoma (1); neuroblastoma (1); neurodegenerative disease (1); Nystagmus (1); oral squamous cell carcinoma (1); postmenopausal osteoporosis (1); primary biliary cirrhosis (1); prostatic adenocarcinoma (1); sarcoma (1); Seizure (1); squamous cell carcinoma (1); triple-negative breast carcinoma (1); virus infection (1).